EPCAM (epithelial cell adhesion molecule)
Diseases named in the same sentence as EPCAM in open-access papers (continued):
Sharing a sentence is not in itself a finding about the gene and the disease.
tumor (continued). "In one preclinical study, using EpCAM-targeting CAR T cells resulted in effective tumor control in a mouse model." (PMID 40607417, 2025). "The EpCAM expression of normal pancreas epithelium should be quantified and compared to tumor cells in ADCC to determine the viability of EpCAM as a mAb target." (PMID 40358156, 2025). "The neoplasm (regarded as tumor tissue in this sample) boundary was then refined using EPCAM expression, consistent with established FISH workflows." (PMID 40667282, 2025). "While monovalent EpCAM-targeted CAR-T therapy has demonstrated efficacy in eradicating various solid tumors, it has also been associated with tumor recurrence." (PMID 40977703, 2025). "On the other hand, KDM6B was found to mediate the promoting effect of epithelial cell adhesion molecule (EpCAM) on tumor proliferation in CRC15." (PMID 40959109, 2025). "Alternatively, it is possible that tumor cells which originally exhibited high EpCAM expression undergo epithelial–mesenchymal transition, resulting in decreased EpCAM expression levels, thereby preventing detection by the CellSearch system." (PMID 39743435, 2025). "M701 specifically induces potent cytotoxicity in EpCAM-positive tumor cells, with minimal effects on EpCAM-negative cells, highlighting its potential as a targeted therapeutic agent for EpCAM-expressing cancers." (PMID 41275209, 2025). "By targeting the ubiquitous expression of CD45 on leukocytes, this approach enabled a significant enrichment of tumor cells, demonstrating superior efficacy compared with EpCAM‐based selection alone." (PMID 40525275, 2025). "CellSearchTM, which uses anti-EpCAM antibodies for circulating tumor cell (CTC) detection, is currently the only FDA-approved CTC detection in blood." (PMID 40075672, 2025). "The findings suggest that CD44, CD90, CD133, and EpCAM were enriched in HCC tumor tissues, supporting their role in hepatocarcinogenesis." (PMID 40791212, 2025). "Our study provides insights into the demographic and clinicopathological landscape of HCC and highlights the elevated expression of CD44, CD90, CD133, and EpCAM in tumor tissues." (PMID 40791212, 2025). "The aim of this review is to reveal the role of the EpCAM in circulating tumor cell isolation, addressing its limitations due to the heterogeneity of CTCs and the epithelial-to-mesenchymal transition." (PMID 40076201, 2025). "MPEs are characterized by a heterogeneous cellular composition, primarily composed of immune cells (CD45+) and tumor cells (EpCAM+)." (PMID 40525275, 2025). "Nevertheless, our gating strategy allowed partial discrimination between endocervical and tumor-derived EpCAM+ cells based on expression intensity." (PMID 41154384, 2025). "Again, EpCAM CAR-T cells significantly promoted tumor eradication except one mouse in BB CAR-T cell group." (PMID 41417221, 2025). "Clinical studies have shown persistent EpCAM expression in HCC patients even after curative tumor resection, suggesting a role in recurrence." (PMID 40791212, 2025). "In conclusion, the EpCAM gene plays a vital role in tumor development and progression, and its elevated expression in tumors makes it a potential therapeutic target." (PMID 41357552, 2025). "In immunodeficient mice, the majority of tumor cells (mCherry + ) was also positive for EpCAM throughout the DN, MRD, and REL phases." (PMID 40738896, 2025). "To further evaluate the anti-tumor activity and potential toxic effect of EpCAM CAR-T cells, we conducted the in vivo study to validate the findings in vitro." (PMID 41417221, 2025). "In the CellSearch system, this is partly overcome by so‐called “controlled aggregation”, which increases the capture of tumor cells with low EpCAM antigen density." (PMID 39743435, 2025).
tumor (continued). "Silica‐coated magnetic nanobeads functionalized with streptavidin (NC@silica‐SA) efficiently capture circulating tumor cells (CTCs) with varying EpCAM expression." (PMID 39743435, 2025). "Engineered macrophages expressing CARs specific to tumor-associated antigens, such as HER2 or epithelial cell adhesion molecule (EpCAM), exhibit robust phagocytic activity and direct tumoricidal effects." (PMID 40333213, 2025). "Circulating tumor cells (CTCs) were detected through the expression of epithelial markers (EPCAM, EGFR, and MET)." (PMID 40616388, 2025). "Elevated expression of EpCAM can drive sustained proliferation and tumor or metastatic growth, potentially leading to poor prognosis for the patient." (PMID 40445498, 2025). "Expression analyses revealed increased EGFR and TF levels with advancing tumor stage, whereas EpCAM expression declined in advanced-stage tumors." (PMID 40806559, 2025). "Both are DARPin-fused to distinct TAAs (HER2, EGFR, and EpCAM), so the cage and key must co-localise on the tumour cell surface." (PMID 41465327, 2025). "For EGFR- and EpCAM-positive HCT116 cells, a 100-fold increased cell killing activity was detected compared to EGFR-positive or EpCAM-positive tumor cells." (PMID 40936895, 2025). "Low-affinity antibodies are more likely to bind selectively to cells with extremely high EpCAM expression and penetrate deeper by avoiding ‘binding barrier’ to distribute less heterogeneously in the tumour tissue, reducing off-target effects." (PMID 40792441, 2025). "The CellSearch platform, approved by the FDA, identifies cells in blood that express cytokeratin or the epithelial cell adhesion molecule.CTCs aid in the development of novel treatments and offer insights into the biology of tumours." (PMID 40027232, 2025). "Among these markers, the highest mean GMF levels were observed for EpCAM and cytokeratin, which are well-known markers of epithelial malignancies, further supporting the presence of tumor cells in LNs." (PMID 39941799, 2025). "The signaling of EpCAM crosstalk with other molecules is involved in the function of CSCs in tumor development." (PMID 39996844, 2025). "The Epithelial Cell Adhesion Molecule (EpCAM) and other epithelial markers have been the cornerstone in the detection and capture of circulating tumor cells (CTCs) through liquid biopsy techniques." (PMID 40076201, 2025). "We utilized EpCAM expression as a biomarker to identify tumor cells within MPEs using flow cytometry." (PMID 40525275, 2025). "The identified anti-EpCAM sdAbs exhibit substantial anti-tumor activity both in vitro and in vivo, suggesting they are strong candidates for future therapeutic applications in cancer therapy." (PMID 40017594, 2025). "Simultaneously, systemic spread was assessed by the presence of circulating tumor cells (CTCs) in peripheral venous blood using both the EpCAM-dependent CellSearch and the size-dependent Parsortix systems in parallel." (PMID 40361138, 2025). "This transition enhances the metastatic potential of tumor cells but also hinders their detection using EpCAM-based methods." (PMID 40076201, 2025). "The inhibitor VB4–845 targeting EpCAM+ Liver-CSCs shows anti-tumor cytotoxicity, especially combined with 5-FU." (PMID 41438763, 2025). "Tumor cells were identified using EPCAM, KRT18, and AFP as markers, while T/NK cells were identified by using the markers CD3D, CD3E, and GZMA." (PMID 40740783, 2025). "CX-2051 is a masked, conditionally activated Probody ADC that targets EpCAM, armed with a topoisomerase-1 inhibitor payload, designed to overcome safety challenges of EpCAM targeting by releasing its payload only in the tumor microenvironment." (PMID 41219972, 2025). "The beads significantly improved capture efficiency of low EpCAM tumor cells compared to the CellSearch system, though with increased leukocyte co‐enrichment." (PMID 39743435, 2025).
tumor (continued). "EpCAM expression was decreased in lung tissue but remained elevated in the liver, suggesting a tissue-selective effect on tumor cell presence." (PMID 40958869, 2025). "Combining HER2 and EGFR with EpCAM in circulating tumor cell enrichment strategies enhances the capture of heterogeneous CTC populations, addressing the limitations of solely relying on EpCAM-based methods." (PMID 40076201, 2025). "Transcriptomic profiling revealed that PDGCOs_1 expressed elevated levels of tumor epithelial and stem cell markers, such as EPCAM, CDH1, ALDH3A1, CA9, CD24, and CD133." (PMID 40723172, 2025). "EGFR and TROP2 emerged as broadly expressed and therapeutically actionable targets, while TF and EpCAM showed potential in specific tumor contexts." (PMID 40806559, 2025). "We focused on 3 stem/progenitor markers, KRT19, EPCAM, and PROM, which are known to be associated with tumor aggressiveness." (PMID 40038575, 2025). "So, anti-tumor effect of the five human anti-EpCAM sdAbs was evaluated with three EpCAM+ cancer cell lines (DU145, PC3 and MCF-7)." (PMID 40017594, 2025). "Focused on this cluster number “3”, cells from the three samples were found to express some epithelial/tumor markers at distinct levels, with markers including EPCAM, CD44, KRT8, ITGA6, and CLDN4." (PMID 41440935, 2025). "The TVC yields ranged from 2.7 × 109 to 77.1 × 109 cells, encompassing the expected target dose range (1 × 109–150 × 109 cells), while tumor cell impurities (TROP2+/EPCAM+) remained minimal (<0.1%)." (PMID 40806287, 2025). "Consistently, immunohistochemical staining for EpCAM, a marker of epithelial tumor cells, confirmed these findings, showing markedly reduced tumor cell colonization in the lungs of fruquintinib-treated animals compared to controls." (PMID 41459512, 2025). "In line with this notion, we detected NOTCH3+/HTR2B + cells within the EpCAM + epithelial and tumor cell population in CRC tissues." (PMID 41034989, 2025). "This novel BsADC demonstrated significant cytotoxicity against various tumor cell lines expressing EpCAM and CLDN3 both in vitro and in vivo." (PMID 40057807, 2025). "Circulating tumor cells (CTCs) are tumor cells derived from primary tumors that can be categorized as epithelial (EpCAM+Vimentin−), mesenchymal (EpCAM−Vimentin+), and hybrid (EpCAM+Vimentin+) types." (PMID 40995085, 2025). "It seems that although PC3 tumor cells express low levels of EpCAM due to their high expression in cancer stem cells, using these CAR T cells can lead to improving symptoms in PC mouse models." (PMID 40607417, 2025). "Vaccination with CD44/EpCAM peptide-primed dendritic cells enhances anti-tumor immunity and induces apoptosis." (PMID 41438763, 2025). "Clinical studies so far with the anti-EpCAM mAbs for cancer therapy showed only the low success with limited anti-tumor effects, which highlights the need for the development of more efficacious anti-EpCAM antibody drug candidates." (PMID 40017594, 2025). "This system employs platinum electrodes functionalized with EpCAM antibodies for tumor-exosome capture, and an additional EpCAM antibody tagged with a reporter is used for signal amplification." (PMID 40305328, 2025). "Future studies aimed to evaluate the in vivo anti-tumor activity of EpCAM-ReTARGTPRIFNαR149A should use tumor-bearing mice engrafted with peripheral blood mononuclear cells (PBMCs) from CMV-seropositive/HLA-B*07:02-matched donors." (PMID 40243928, 2025). "CX-2051 illustrates a viable, tumor-selective way to “drug” EpCAM in CRC; expansion cohorts will clarify durability, dose, and risk mitigation." (PMID 41256852, 2025). "In contrast, no significant grade-dependent differences were observed for EGFR or EpCAM in our cohort, although other studies have reported a positive association between EGFR expression and tumor grade." (PMID 40806559, 2025).
tumor (continued). "Exosomes were combined with MHCI antibodies on the chip to separate certain tumor-associated exosomes, and they were then stained by immunofluorescent for HER2 and EpCAM." (PMID 40305328, 2025). "Biodistribution studies in mice bearing EpCAM-expressing SKOV-3 xenografts showed that [68Ga]Ga-Ec1-NOTA had lower uptake in most normal organs while maintaining tumor uptake." (PMID 40445498, 2025). "Other potential targets, including HSPs and tumor stem cell markers such as epithelial cell adhesion molecule EpCAM, have also demonstrated roles in promoting antigen delivery and enhancing immune activity, providing multiple options for HCC vaccine research." (PMID 40432108, 2025). "EpCAM is a homophilic cell-cell adhesion glycoprotein and is expressed on CSCs in epithelial tumors and circulating tumor cells." (PMID 40017594, 2025). "To verify that TBX21 knockdown occurred specifically within tumor epithelial cells, we performed double immunofluorescence staining for TBX21 with EpCAM (tumor epithelial marker) and CD3 (T-cell marker)." (PMID 41573646, 2025). "Our BsADC molecules have strong binding activities to tumor cells with high EpCAM and CLDN3 expression, and also exhibited stronger ADCC, ADCP, and CDC effects than their parental bivalent antibodies on OVCAR-3 cells." (PMID 40057807, 2025). "An example is the bi-functional DNA aptamer TEPP that binds to both transferrin receptor (TfR) located on BBB endothelia cells and to the epithelial cell adhesion molecule (EpCAM) located on tumor cells within the brain." (PMID 40716251, 2025). "Epithelial cell adhesion molecule (EpCAM), a homophilic cell–cell adhesion glycoprotein, is a well-known tumor antigen expressed in various types of epithelial tumors." (PMID 40057807, 2025). "Subsequently, three tumor cell lines with varying EpCAM densities were spiked into 7.5 mL blood, and the performance of our method was compared with the clinically validated CellSearch system." (PMID 39743435, 2025). "Barnase-tagged DARPins targeting HER2/EpCAM induced dose-dependent cytotoxicity, cytokine release, and in vivo tumour clearance." (PMID 41465327, 2025). "Blockade of NE during the neutrophil-mediated induction phase modulated EpCAM expression, resulting in recovery of tumor cell proliferation, reduced tumor cell migration and reduced CAM tumor growth and angiogenesis." (PMID 40155451, 2025). "EpCAM staining of epithelial tumor cells shows a change in tumor morphology in the IL-1RA-treated group compared to the control group." (PMID 40563856, 2025). "Using the FETCH magnetic separation system, we validated the capture efficiency of our beads on tumor cells with varying EpCAM expression." (PMID 39743435, 2025). "The IFP-regulated TGF-β signaling is also a contributing mechanism to the antigen heterogeneity in solid tumors, as it can downregulate epithelial cell adhesion cofactor (EpCAM) expression on the surface of tumor cells." (PMID 40969762, 2025). "In contrast, the loss or reduced EpCAM expression contributes to the induction of EMT, allowing tumor cells to acquire migration, invasion, and metastatic abilities." (PMID 40699639, 2025). "It depicts the mechanism by which CAR-T cells recognize and bind to specific tumor-associated antigens, including folate receptor alpha (FRα), mucin-1 (MUC1), and epithelial cell adhesion molecule (EpCAM)." (PMID 40281554, 2025). "EpCAM plays a pivotal role in the process of epithelial carcinogenesis, with research indicating that it is crucial for tumor cell adhesion, proliferation, migration, and epithelial-mesenchymal transition." (PMID 41357552, 2025). "Although EpCAM is a known epithelial tumor marker, this is the first study looking at EpCAM as a target for IMI of LNs with cancer cells." (PMID 41087662, 2025). "CD90(+) CTCs, DCP, and AFP showed significant alterations corresponding to tumor size changes, whereas EpCAM(+) CTCs only increased in progressive cases." (PMID 40940925, 2025).
tumor (continued). "In the Huh7 cell line, double-labeled CD133+EpCAM+ cells demonstrate the greatest tumor-initiating capacity, need only 500 of these cells to successfully generate tumors." (PMID 40710326, 2025). "Flow cytometry comparing cells dissociated from a primary tumor to its matched tumoroid culture confirmed the enrichment of EpCAM-positive and CEACAM-positive cells and a reduction in CD45-positive and CD31-positive cells during tumoroid establishment." (PMID 39890889, 2025). "The TME analysis 7 days after a single dose of aCD40 revealed fewer EpCam + tumor cells and a lower proportion of Ki67 + proliferating tumor cells in treated tumors." (PMID 40585246, 2025). "Further research is warranted to elucidate the complex role of EpCAM in tumor biology and to develop targeted therapies that effectively disrupt its function within the TME while minimizing adverse effects on normal tissues." (PMID 39996844, 2025). "Despite efforts using anti-EpCAM monoclonal antibodies (mAbs), their anti-tumor effects have been limited." (PMID 40017594, 2025). "Epithelial cell adhesion molecule (EpCAM), a tumor antigen for antibody–drug conjugates (ADCs), is highly expressed in many epithelial cancers." (PMID 40057807, 2025). "EPCAM, also known as CD326, is overexpressed in many human cancers, and its expression is closely associated with EMT of tumor cells." (PMID 41551611, 2025). "Multiplex IHC staining showed that DLL4 and EpCAM were co-localized in tumor cells with low expression of TTN." (PMID 41326912, 2025). "Epithelial malignant tumor cells typically express the epithelial marker EpCAM on their surface; however, they often undergo epithelial-mesenchymal transition (EMT), leading to the loss of EpCAM and the expression of mesenchymal markers such as vimentin." (PMID 40718490, 2025). "The 4 CTC-derived cell lines replicate the structure and morphology of the tumor of origin, as well as EpCAM positivity, the marker of choice for CTCs of epithelial origin." (PMID 40157906, 2025). "The EpCAM staining of the corresponding primaries of each patient revealed the presence of EpCAM already in the primary tumor." (PMID 40617497, 2025). "Employing a novel algorithm capable of super‐resolution analysis of tumour ecosystems,15we first identified tumour cells based on the expression of EPCAM, TG, KRT18 and KRT19." (PMID 39810624, 2025). "Previous studies have reported the development of BiTEs against other tumor-associated antigens, including ROR1, EpCAM, and HER2, with encouraging efficacy across solid tumors." (PMID 41009508, 2025). "EpCAM is highly expressed in GC, and its inhibition has been shown to significantly suppress tumorigenesis and tumor progression." (PMID 40977703, 2025). "All the conjugates targeted specifically EpCAM-expressing xenografts in mice, as the tumor uptake was significantly lower in Ramos xenografts (EpCAM-negative) compared with SKOV-3 xenografts (EpCAM-positive)." (PMID 40445498, 2025). "The minicircle DNA stably expressed bispecific T cell engager (BiTE) anti-CD3/anti-EpCAM, thus enhancing tumor localization and CTLs recognition, significantly inhibiting tumor growth." (PMID 40006592, 2025). "L-685,458 and DAPT inhibit proliferation and stemness of EpCAM+ Liver-CSCs, while PF-03084014 reduces self-renewal and tumor growth in vivo and shows synergy with sorafenib." (PMID 41438763, 2025). "Tumor cells were defined as EpCAM+ CD90− CD140a− CD45− CD33− CD14− and further analyzed for the expression of CD24 and CD44, two markers associated with tumor aggressiveness and stem-like features." (PMID 40877861, 2025). "In a similar approach, we identified the cell cluster of ADC and confirmed the tumor cells cluster based on the expression of EPCAM and KRT18." (PMID 40597205, 2025). "Tumor clusters c1–c4 exhibited relatively high expression of EPCAM and KRT18, with c4 showing elevated IGF2 expression." (PMID 40098972, 2025).